WNT5A (Wnt family member 5A)
Diseases named in the same sentence as WNT5A in open-access papers (continued):
Sharing a sentence is not in itself a finding about the gene and the disease.
melanoma (continued). "Most interestingly, the ability of WNT5A to stimulate the invasiveness of MARCKS siRNA-silenced melanoma cells was completely abolished, suggesting an essential WNT5A-downstream signaling role of MARCKS in its ability to induce melanoma cell invasion." (PMID 32033033, 2020). "In this context, WNT5A signaling has been identified as an important cascade in melanoma progression and metastasis." (PMID 32033033, 2020). "Rather, the WNT5A/PKC signal has been shown in melanoma cells to result in an EMT process that was suggested to explain how this signaling pathway caused elevated invasion leading to increased metastasis." (PMID 32033033, 2020). "Previously, it has been shown that HuR stabilizes WNT5A and thereby positively influences melanoma cell migration." (PMID 32455577, 2020). "Wnt2 is overexpressed in many stages of the development of colorectal cancer, and Wnt5a is overexpressed in breast cancer, colorectal cancer, lung cancer, prostate cancer and melanoma." (PMID 33310972, 2020). "WNT5A is a well-known mediator of melanoma cell invasion and metastasis via its ability to activate protein kinase C (PKC), which is monitored by phosphorylation of the endogenous PKC substrate myristoylated alanine-rich c-kinase substrate (MARCKS)." (PMID 32033033, 2020). "An important pathway that has been shown to be crucial for WNT5A-mediated melanoma invasion and metastasis is the protein kinase C (PKC) signaling pathway, as demonstrated in several studies by Weeraratna and coworkers." (PMID 32033033, 2020). "Previously, the phosphorylation status of the MARCKS protein has only been used as an indicator of WNT5A-mediated PKC activation in melanoma cells." (PMID 32033033, 2020). "Since MARCKS phosphorylation hinders its actin cross-linking ability, we wanted to study the consequence(s) of WNT5A-mediated MARCKS phosphorylation for the F-actin network of melanoma cells." (PMID 32033033, 2020). "Based on these results, we decided to focus on the Ser-159/163 phosphorylation of the MARCKS protein and how it relates to WNT5A signaling and melanoma cell invasion." (PMID 32033033, 2020). "This approach allowed us to completely abolish WNT5A-induced melanoma cell invasion, thus demonstrating for the first time a crucial role of MARCKS phosphorylation in WNT5A-driven melanoma cell invasion." (PMID 32033033, 2020). "Our results reveal that Wnt5a stimulates melanoma cells to secrete IL-6, IL-8, IL-11, MCP-1, IL-6sR, and sTNFRI." (PMID 31510045, 2019). "Wnt5a has garnered interest in melanoma after the observation that it is highly expressed in metastatic melanoma and that its high expression correlates with disease progression and decreased progression-free and overall survival." (PMID 31510045, 2019). "The elevated Wnt5a expression seen in both melanoma metastasis and melanoma cell lines with an invasive phenotype made it feasible to study the Wnt5a/NF-κB crosstalk by using strategies based on the inhibition of endogenous Wnt5a." (PMID 31510045, 2019). "We next checked for increased WNT5A expression, which is another established characteristic of BRAFi resistance in melanoma." (PMID 30582770, 2019). "Our work shows NF-κB activation by Wnt5a, identifies critical intermediaries of this process, and demonstrates that Wnt5a stimulates secretion of cytokines/chemokines in melanoma cells." (PMID 31510045, 2019). "The WNT family member WNT5A was originally shown to promote melanoma cell migration by Weeraratna and co‐workers." (PMID 30582770, 2019). "Our observation of elevated IL‐6 secretion is in accordance with the observation that IL‐6 is not only a promoter of melanoma metastasis but also an inducer of WNT5A protein expression in parental BRAFi‐sensitive melanoma cells." (PMID 30582770, 2019).
melanoma (continued). "To evaluate the independent and combined effects of IL‐6 and WNT5A signalling on the invasive migration of BRAFi‐R melanoma cells, we first blocked WNT5A or IL‐6 signalling separately in HTB63‐R and A375‐R cells by using either Box5 or an IL‐6 Ab." (PMID 30582770, 2019). "On the other hand, a protumorigenic role for Wnt5a has been shown for T-cell leukemia, melanoma, gastric cancer, non-small-cell lung cancer, pancreatic cancer, and prostate cancer." (PMID 31510045, 2019). "We have previously reported the existence of an IL‐6/WNT5A positive feedback loop in parental BRAFi‐sensitive melanoma cells that is related to their migratory and invasive properties." (PMID 30582770, 2019). "In the five melanoma cell lines analyzed, stimulation with Wnt5a for 30 min significantly phosphorylates Akt at S473, a well-known marker of Akt activity." (PMID 31510045, 2019). "Despite the absence of an IL‐6/WNT5A loop, we found that both an IL‐6 blocking antibody and the WNT5A antagonist Box5 alone impaired the elevated invasive migration of BRAFi‐R melanoma cells, but combined use of the two was more effective." (PMID 30582770, 2019). "In this study, we demonstrate for the first time that the induction of BRAFi‐R in melanoma cells results in a prominent amplification of IL‐6 secretion along with elevated WNT5A expression." (PMID 30582770, 2019). "With the exception of IL-6, the level of these cytokines in primary melanoma tumors also significantly correlated with that of Wnt5a (red symbols)." (PMID 31510045, 2019). "Based on our present observations, we conclude that simultaneous inhibition of IL‐6 and WNT5A signalling effectively obstruct Cdc42‐dependent migration and invasion of BRAFi‐R melanoma cells." (PMID 30582770, 2019). "Since then, the investigation of its role in invasion and metastasis has been a staple of Wnt5a research in melanoma and other tumor types." (PMID 31510045, 2019). "To investigate the importance of this signalling molecule, we next blocked IL‐6 and WNT5A signalling as well as Cdc42‐GTPase activation itself in BRAFi‐R melanoma cells and studied how these treatments affected the cellular actin network." (PMID 30582770, 2019). "This is highlighted by findings that melanoma-derived Wnt5a effected a metabolic shift in DCs from glycolysis to oxidative phosphorylation, which was attributed to β-catenin- and PPARγ-mediated cellular activation." (PMID 31781093, 2019). "IL-6 was shown to initiate the secretion of WNT-5a in melanoma cells and human bone marrow stromal cells, respectively." (PMID 32195204, 2019). "Taken together, these results indicate that Wnt5a activates the NF-κB pathway and has an immunomodulatory effect on melanoma through the secretion of cytokines and chemokines." (PMID 31510045, 2019). "The treatment of melanoma cells with Wnt5a induced phosphorylation of the NF-κB subunit p65 as well as IKK phosphorylation and IκB degradation." (PMID 31510045, 2019). "Illustrating the importance of this pathway, these studies also showed that the genetic silencing of Wnt5a in melanoma resulted in a significant influx of activated tumor antigen-specific CD8+ T cells." (PMID 31921140, 2019). "Altogether, our study demonstrates that the development of BRAFi‐R in melanoma cells triggers a significant increase in IL‐6 secretion along with elevated WNT5A protein expression." (PMID 30582770, 2019). "In the present study, we provide a comprehensive description of the signaling proteins that are activated by Wnt5a and result in NF-κB activation and upregulation of cytokine secretion in melanoma." (PMID 31510045, 2019). "M2 melanoma cells were transfected with an NF-κB synthetic luciferase reporter construct and stimulated with Wnt5a for different time intervals." (PMID 31510045, 2019).
melanoma (continued). "WNT5A was subsequently further investigated for its potential role in the clinical outcome of melanoma, and WNT5A protein expression was shown to predict a shorter recurrence‐free survival in a large cohort of melanoma patients." (PMID 30582770, 2019). "Elevated levels of WNT5A have been reported in melanomas, lung cancer, breast cancer, and gastric cancer." (PMID 31504033, 2019). "To evaluate the relationship between Wnt5a and these cytokines/chemokines in melanoma samples, we used cBioPortal to determine the co-expression of some of these genes with Wnt5a in TCGA public datasets for melanoma (SKCM, 479 patients)." (PMID 31510045, 2019). "Our present study suggests a possible therapeutic potential for a future IL‐6/WNT5A‐based antimetastatic approach for BRAFi‐R melanoma patients." (PMID 30582770, 2019). "Consistent with the findings of elevated IL‐6 secretion and WNT5A expression, we observed increased migration and invasion of these BRAFi‐R melanoma cells compared with their parental HTB63, A375 and A2058 cells." (PMID 30582770, 2019). "To investigate the importance of IL‐6 and WNT5A signalling for the increased invasive migration of BRAFi‐R melanoma cells, we separately or in combination blocked these signalling molecules." (PMID 30582770, 2019). "We also evaluated the role of Akt, a protein kinase that was shown to be a target of Wnt5a in lung cancer and melanoma cells." (PMID 31510045, 2019). "In melanoma, Wnt5a positively regulates many of these processes and has been signaled as a promising therapeutic target." (PMID 31510045, 2019). "In melanoma, Wnt5a correlates with tumor progression and has been shown to play an important role in epithelial mesenchymal transition (EMT) and cell migration." (PMID 29453334, 2018). "Together, these results indicate Wnt5a signaling in melanoma cells induces APT1 phosphorylation at serine residues 209 and 210 and our phospho-specific antibodies are selective for these sites." (PMID 29648538, 2018). "Melanoma cells primarily use glycolysis as an energy source for cell motility and, in this sense, WNT5A acts as a positive modulator by promoting both migration and aerobic glycolysis." (PMID 30166456, 2018). "Wnt5a mediated melanoma cell invasion is reduced by treatment with a small molecule inhibitor of APT proteins." (PMID 29648538, 2018). "Previously, the elevated expression of Wnt5a in human melanoma samples and subsequent in vitro studies have suggested a role for Wnt5a in melanoma metastasis." (PMID 29648538, 2018). "In some tumors, such as melanoma, gastric cancer, osteosarcoma, prostate cancer, nonsmall cell lung cancer, nasopharyngeal carcinoma, and pancreatic cancer, Wnt5a is overexpressed and plays the role of an oncogene." (PMID 30079293, 2018). "To confirm the role of Porcn function in Evi regulation without manipulating Wnt expression, we monitored Evi in the colon cancer cell line HCT116, that depends on Wnt secretion and in the melanoma cell line A375, that expresses Wnt5A and Wnt10B endogenously." (PMID 29378775, 2018). "Another safety issue with Foxy5 is based on the findings that WNT5A promotes tumor progression in tumors such as melanoma, oral squamous cell carcinoma, and gastric cancer." (PMID 30171384, 2018). "Low Wnt5a producing WM239A melanoma cells expressing CFP-FLAG tagged wild type APT1 (APT1WT-CFP-FLAG) were treated with purified Wnt5a and APT1 was immunoprecipitated using anti-FLAG magnetic particles." (PMID 29648538, 2018). "WNT5A-treated melanoma cells demonstrated an increase in glycolytic activity with concomitant upregulation in lactate dehydrogenase (LDH) activity, the AKT/mTOR pathway and migration." (PMID 30171384, 2018). "In melanoma cells, sKl reduced cell invasiveness by inhibiting Wnt5A stimulation of μ-calpain-mediated cleavage of Filamin A." (PMID 29250031, 2017).
melanoma (continued). "Our group demonstrated that IL-6, a TLR signaling product, can activate STAT3 with resulting overexpression of Wnt5a in human papillary thyroid carcinoma, melanoma and pancreatic cancer." (PMID 29371911, 2017). "Wnt5a potentiates melanoma metastasis via induction of the epithelial-to-mesenchymal transition in a protein kinase C-dependent manner." (PMID 29085361, 2017). "Previous studies in our laboratory demonstrated that C10 decreased high constitutive TLR3 and Wnt5a expression in human malignant melanoma, papillary thyroid, and pancreatic cancer cell lines." (PMID 29371911, 2017). "Coincident with this, two recent reports showed that Wnt5A and hypoxia also activate the calpain-mediated cleavage of filamin A and increases melanoma cell motility." (PMID 27206800, 2017). "In contrast, WNT5A has a tumor-promoting role in melanoma where it has been shown to escalate cell migration and invasion, thereby promoting melanoma metastasis." (PMID 29069720, 2017). "Of note, Ekström described the stimulation of exosome release from melanoma cells in vitro with the application of recombinant-WNT5A, as well as the suppression of exosome-release with the application of WNT5A-silencing RNA." (PMID 28796150, 2017). "In this analysis, we found elevated expression of both WNT5A and IL-6 transcripts in invasive melanoma cells." (PMID 27191257, 2016). "A distinct mechanism for Wnt5a induction of melanoma cell motility is through binding to Ror2 and activating of Wnt/Ca+2 signaling, leading to activation of calpain-1, a calcium-dependent non-lysosomal cysteine protease." (PMID 27571105, 2016). "Increased expression and signalling of WNT5A and interleukin-6 (IL-6) have both been shown to promote melanoma progression." (PMID 27191257, 2016). "In three invasive melanoma cell lines, endogenous WNT5A protein expression was related to IL-6 protein secretion." (PMID 27191257, 2016). "Functionally, we demonstrated that combined siRNA knockdown of WNT5A and IL-6 expression or the simultaneous inhibition of WNT5A and IL-6 signalling inhibited melanoma cell invasion more effectively than suppressing each factor individually." (PMID 27191257, 2016). "Box5 antagonizes WNT-5A-induced melanoma cell invasion and prevents β-amyloid peptide-induced WNT-5A-dependent inflammation and neurotoxicity in mouse cortical cultures." (PMID 26514730, 2016). "We recently found that in patient-derived melanoma cell lines, those that were categorized as high in levels of Wnt5a and thus of an invasive phenotype, had dramatically less SOCE than non-invasive melanoma lines." (PMID 27417567, 2016). "Here, we investigated the proposed existence of a WNT5A-IL-6 positive feedback loop that drives melanoma migration and invasion." (PMID 27191257, 2016). "In melanoma cells, WNT-5A activates small GTPase ADP-ribosylation factor 6 (ARF6) via FZD4-LRP6 binding." (PMID 26514730, 2016). "WNT-5A strongly induces cell migration and invasion of melanoma cells, possibly, by inducing epithelial-to-mesenchymal transition (EMT) while decreasing the expression of metastatic suppressors." (PMID 26514730, 2016). "Contrary to its effects in melanoma cells, WNT-5A increases oxidative phosphorylation rates in breast cancer cells demonstrating a context-dependent function of WNT-5A that can also explain its tumor-promoter and tumor-suppressor roles." (PMID 26514730, 2016). "Together, these analyses and our cell line data suggest that WNT5A and IL-6 mRNA expression is poorly correlated in melanoma cells, although their increased expression is characteristic of an invasive melanoma cell phenotype." (PMID 27191257, 2016). "On the other hand, strong expression of WNT-5A is shown in prostate cancer, acute T-cell leukemia, melanomas, and non-melanomas where it correlates with cell motility and tumor invasiveness." (PMID 26514730, 2016).
melanoma (continued). "Extensive WNT-5A expression is detected in human melanoma biopsies where it correlates with the formation of distant metastases and poor prognosis." (PMID 26514730, 2016). "Wnt5a signaling activates the PI3K-AKT pathway in melanoma cells and Wnt3a-induced proliferation involves activation of ERK beside Wnt/β-catenin pathway activation in fibroblasts." (PMID 27323822, 2016). "Conversely, the silencing of WNT5A expression by WNT5A siRNAs or treating WM852 melanoma cells with Box5 (a WNT5A antagonist) significantly reduced IL-6 secretion." (PMID 27191257, 2016). "Using a co-culture experiment, depletion of Wnt5a in melanoma cells decreased endothelial cell branching while stimulation of endothelial cells with isolated melanoma cell exosomes, induced by incubation with rWnt5a, increased endothelial cell branching." (PMID 27571105, 2016). "Increased Wnt5a signaling through Fzd5 in melanoma cells enhanced in vitro motility and invasion through activating PKC that is important in regulating cell cytoskeleton, adhesion, and motility." (PMID 27571105, 2016). "Melanoma’s which develop resistance to treatment with BRAF inhibitor PLX4720 display upregulated Wnt5a which was consequently show to promote tumour growth via FZD7 and AKT." (PMID 27196929, 2016). "Several studies have highlighted the ability of either IL-6 or WNT5A to promote melanoma cell motility." (PMID 27191257, 2016). "The Wnt5a-derived hexapeptide Box5, which inhibits Wnt5a signaling, reduced Wnt5a-induced melanoma cell motility." (PMID 27571105, 2016). "Knock-down of endogenous WNT-5A decreases melanoma cell proliferation and sensitizes them to BRAF inhibitor-induced cell death." (PMID 26514730, 2016). "In melanoma, many of these pathways have been directly shown to participate in WNT5A-driven cell migration and invasion." (PMID 27191257, 2016). "Knockdown with anti-IL-6 siRNAs or treating WM852 melanoma cells with a neutralising anti-IL-6 antibody reduced WNT5A protein expression." (PMID 27191257, 2016). "WNT-5A activates ARF6 in melanoma cells leading to disruption of N-cadherin-β-catenin interaction, enhanced β-catenin-mediated transcription and invasion." (PMID 26514730, 2016). "Expressions of Klotho and WNT-5A are inversely correlated in melanoma tissues, whereas the presence of Klotho suppressed melanoma cell invasion." (PMID 26514730, 2016). "Of significance are the melanoma-related genes NOTCH1, NOTCH2, WNT3a, and WNT5a, each of which are associated with two or more UV-miRNAs that can directly target these respective genes." (PMID 27149382, 2016). "In melanoma cells Wnt5a signaling directs migration and invasion of cells in a PKC-dependent manner and can increase phosphorylated AKT via phosphoinositide 3-kinase (PI3K)." (PMID 27323822, 2016). "Compared to correlation with poor prognosis in gastric cancer and melanomas, Wnt5a was discovered as an antagonist to the canonical Wnt signaling pathway with tumor suppressor activity in differentiated thyroid carcinomas." (PMID 26608372, 2016). "First, the HOPP algorithm revealed that the invasive phenotype of cultured melanoma cells was significantly correlated with increased expression of WNT5A or IL-6." (PMID 27191257, 2016). "This is particularly important as strong staining of both WNT5A and LDH5 is linked with reduced disease-free survival in melanoma patients." (PMID 26514730, 2016). "Surprisingly, in spite of showing features of senescence following treatment with PLX4720 and ionizing radiation, Wnt5a-high melanoma cells were still able to invade and formed colonies in vivo." (PMID 27571105, 2016). "While Wnt5a has been shown to inhibit cell growth, migration and invasiveness of thyroid and colorectal cancer cells, increased Wnt5a expression is involved in aggressiveness of other types of cancers such as melanoma and gastric cancer." (PMID 27571105, 2016).